ALB (albumin)
Diseases named in the same sentence as ALB in open-access papers (continued):
Sharing a sentence is not in itself a finding about the gene and the disease.
sarcopenia (continued). "Another multicentre prospective study found that NLR, PNI, SII and platelet lymphocyte ratio (PLR) were all good predictors of sarcopenia, with ALI [BMI (kg/m2) × albumin (g/dl)/NLR] being the best predictor." (PMID 36046129, 2022). "Second, in the sarcopenia group, low levels of hemoglobin, low levels of serum albumin indicating a low-nutrition status, and elevated levels of BNP were observed in the sarcopenia group." (PMID 35313647, 2022). "Multiple tumors, maximal tumor diameter ≥ 5cm, major venous thrombosis (VP3 and VP4), sarcopenia, AFP ≥ 200 ng/ml, and albumin<3.5mg/dL were allocated with a score of 1.5, 1.5, 3, 1, 2, and 1, respectively." (PMID 36248997, 2022). "With respect to laboratory variables, patients with sarcopenia had a higher CRP (p = 0.003) and lower hemoglobin (p < 0.001), WBC count (p = 0.002), albumin level (p < 0.001), and ALT (p = 0.013)." (PMID 34357140, 2021). "The higher the albumin level was, the higher SMI was and the lower the prevalence of sarcopenia was." (PMID 34608386, 2021). "In the current study, given the prognostic value of ALB, GLB, and sarcopenia in RCC patients, we combined them to construct a new index (CAS), providing a more comprehensive response to systemic nutritional and inflammatory status." (PMID 34631767, 2021). "Kaplan-Meier curves were employed to analyze the impact of albumin-globulin ratio (AGR), albumin-globulin score (AGS), sarcopenia, and CAS on overall survival (OS) and cancer-specific survival (CSS) in RCC patients." (PMID 34631767, 2021). "Furthermore, we assessed whether frailty and comorbidities, tumor complexity and other parameters, such as ASA score, single kidney, albumin level or sarcopenia, are determining factors for the therapeutic strategy patients and clinicians choose as treatment for renal masses." (PMID 33515329, 2021). "The 12 variables were as follows; sex, pathology, ECOG, carbohydrate antigen 19-9 (CA 19-9), CRP, albumin, protein, cholesterol, BUN, NLR, Sarcopenia, group stratification based on sarcopenia and NLR." (PMID 32984018, 2020). "Our study also showed correlations with serum markers, such as albumin and ferritin, more significant in sarcopenic with respect to non-sarcopenic individuals, thus supporting the evidence that nutritional status may mediate the relationship between sarcopenia and myomiRs." (PMID 31979011, 2020). "Pre-RT sarcopenia group had higher PIVKA-II (p = 0.001), lower serum total protein level (p = 0.027), lower serum albumin level (p = 0.015), and lower percentage of overweight/obesity BMI (p < 0.001)." (PMID 31681607, 2019). "The highest PLR level group had a higher prevalence of sarcopenia, a lower SMI and a slower gait speed; moreover, this group was older, had a higher C-reactive protein (CRP) and lower albumin levels." (PMID 29192175, 2017). "There was a significant positive correlation between sarcopenia and the indexes of DBP, ALB, and Cr (P > 0.05)." (PMID 28701179, 2017). "Albumin, although commonly used to assess nutritional status, did not identify sarcopenia in our cohort." (PMID 40912688, 2026). "Based on this knowledge, we speculated that the CRP/albumin ratio might be an even better marker of inflammation than CRP or albumin alone in relation to nutritional status and sarcopenia." (PMID 41345186, 2025). "Albumin levels showed significant differences between the groups, with lower levels observed in patients with sarcopenia (3.36 ± 0.52 g/dL) compared to those without sarcopenia (3.60 ± 0.62 g/dL)." (PMID 40725756, 2025). "Regarding laboratory values, HbA1c, eGFR, albumin, and hemoglobin levels were considerably lower in the group with sarcopenia than in the group without it." (PMID 41393007, 2025). "The albumin level in patients without sarcopenia (33.5 (22.7–44.3 g/dL)) was found to be significantly higher than in patients with sarcopenia (31.1 (19.3–42.9 g/dL)) (p = 0.033)." (PMID 40005385, 2025).
sarcopenia (continued). "Consistently with the literature, our study found that patients with sarcopenia had significantly lower serum albumin levels than those without sarcopenia." (PMID 40428779, 2025). "In this study, patients with sarcopenia showed significantly higher MQSGA scores and lower serum albumin levels than those without sarcopenia." (PMID 41283022, 2025). "Prior to this consensus, studies primarily emphasized the role of nutritional indicators – such as albumin and body composition – in LT prognosis, yet lacked standardized, objective measures for assessing sarcopenia." (PMID 41211064, 2025). "The secondary objectives were to find out whether there is any correlation of sarcopenia with C-reactive protein (CRP), erythrocyte sedimentation rate (ESR), albumin, and hemoglobin levels." (PMID 40476129, 2025). "Unfortunately, our study did not collect data on key indicators of nutritional status or sarcopenia, such as serum albumin levels, body mass index or muscle mass assessments." (PMID 40299543, 2025). "Hemoglobin and albumin were lower, and CRP and ESR were higher in the sarcopenia group." (PMID 40476129, 2025). "Studies have shown that the serum albumin of the older adults with sarcopenia is lower than that of the non-sarcopenia older adults participants." (PMID 40969368, 2025). "The secondary objectives were to find out whether there is any correlation between sarcopenia with CRP, ESR, albumin, and hemoglobin levels." (PMID 40476129, 2025). "Additionally, in terms of laboratory tests, higher ALB, Hb, TRF and TLC were proven to be protective factors for the development of sarcopenia." (PMID 41280389, 2025). "Studies have shown that plasma albumin levels are higher in elderlyindividuals without sarcopenia compared to those with sarcopenia." (PMID 39076344, 2024). "Participants with sarcopenia tend to be older, to have higher sedentary physical activity, and demonstrate differences in total cholesterol, triglycerides, hemoglobin, total protein, HDL cholesterol, serum albumin, and calf circumference." (PMID 38167445, 2024). "In multivariate analysis, albumin and sarcopenia were not independent prognostic factors for OS (all p > 0.05)." (PMID 39456597, 2024). "Serum total protein levels (p = 0.001), albumin levels (p < 0.001), albumin ratio (p < 0.001), and prealbumin level (p < 0.001) in patients with sarcopenia were significantly lower than patients without sarcopenia." (PMID 38438954, 2024). "Few sarcopenia group variables, such as BMI, serum albumin, and Hb were reduced relative to the non-sarcopenia group (p < 0.05)." (PMID 38699840, 2024). "The incidence ofmortality was higher in patients screened for sarcopenia; in those with nutritionalrisk, low BMI, or low muscle mass based on the CC; and in those with severemalnutrition assessed on the basis of the SGA and serum albumin level." (PMID 39540014, 2024). "The JOA hip score, UCLA activity score, and albumin level were significantly lower in the no sarcopenia assessment group than in the severe sarcopenia group (Table A1)." (PMID 38999833, 2024). "A meta-analysis of 14 studies revealed significantly lower serum ALB levels in sarcopenic elderly individuals compared to those without sarcopenia." (PMID 40008206, 2024). "The putative effects of sarcopenia on MACE were possibly not mediated by a causal pathway involving CACS, CRP, serum albumin, or vitamin D levels." (PMID 39315011, 2024). "The albumin (p = 0.003), Hb (p = 0.003), PT (p = 0.006), INR (p = 0.007), Child-Pugh score (p < 0.001), MELD score (p = 0.008), ascites (p = 0.005), sarcopenia (p < 0.001) and NSBBs (p = 0.018) were the potential factors that predicted 2-year rebleeding in univariable regression analysis." (PMID 38699840, 2024). "Although serum albumin levels were optimized before pouch construction, other factors, such as sarcopenia and American Society of Anesthesiologists grade, were not considered during the analysis." (PMID 39759750, 2024).
sarcopenia (continued). "Albumin, sodium, and platelet levels were significantly lower in the group with both sarcopenia and frailty than in those without these two complications." (PMID 39795544, 2024). "In the inter-group comparison, advanced age, female sex, low BMI, low serum albumin levels, low total FIM score, reduced calf circumference, low grip strength, possible sarcopenia, low SPPB score, and low MMSE-J score made discharging significantly more difficult." (PMID 37442988, 2023). "In hospitalised people with CHD, albumin and transthyretin levels are lower in the presence of sarcopenia (as defined by the Asian Working Group for Sarcopenia) compared to those defined as non-sarcopenic." (PMID 36891188, 2023). "So far, the prognostic significance of CRP/albumin ratio in the aging and inflammatory processes in sarcopenia has not been reported." (PMID 37465171, 2023). "Intriguingly, we showed that patients with probable sarcopenia had significantly lower serum albumin levels than their peers without sarcopenia." (PMID 37363476, 2023). "Adverse events (AEs) frequently occurred, and the albumin-bilirubin score significantly decreased after atezo/bev therapy in the sarcopenia group than in the non-sarcopenia group." (PMID 37370853, 2023). "Additionally, when considering sarcopenia as a grouping factor, notable disparities were noted in terms of BMI (P < 0.001), FEV1% (P < 0.001), and pre-albumin levels (P = 0.006) within the various groups." (PMID 38090498, 2023). "First, the cut-off values of albumin and GNRI 98 and 105, but not that of CONUT, were associated with a diagnosis of sarcopenia in the overall, men and women groups." (PMID 36819693, 2023). "However, when the cut-off for sarcopenia was analysed by ANOVA in relation to the continuous variables of the biomarkers, the results showed that sarcopenia correlated significantly with albumin (p < 0.01), Hb (p < 0.01), TNFα (p = 0.02) and CRP (p < 0.01)." (PMID 37906352, 2023). "In the Cox proportional hazards model, low Na was a significant prognostic factor in ACLD (hazard ratio (HR) 5.33, p < 0.01); however, the albumin-bilirubin (ALBI) score (HR 2.49) and sarcopenia (HR 4.03) were extracted in the multivariate analysis (p < 0.05 both)." (PMID 37664343, 2023). "Both the more marked hormonal changes in liver cirrhosis and the more intense sarcopenia may explain the relationship between OSO osteoporosis and variables related to liver function, such as prothrombin activity or serum albumin." (PMID 37373124, 2023). "The distribution of scoring of lymphocyte count, total cholesterol, and albumin was not different between the sarcopenia– and sarcopenia+ groups." (PMID 36819693, 2023). "C-reactive protein (CRP) (p = 0.011) and CRP/albumin ratio (p = 0.030) as well as IL-1β (p = 0.002), cfDNA (p < 0.001) and bilirubin levels (p = 0.002) were significantly higher in the sarcopenia group as opposed to the no sarcopenia group." (PMID 37465171, 2023). "Sarcopenia was significantly more common in patients who had smoked (p = 0.038) or drunk (p = 0.041) regularly, or those who had a low KPS score (p = 0.002) or low albumin (p = 0.023)." (PMID 36969820, 2023). "Preoperative nutritional assessment via laboratory data revealed that patients with sarcopenia had lower serum haemoglobin and albumin levels than patients without sarcopenia." (PMID 36969080, 2023). "In the present study, the levels of albumin and prealbumin were significantly lower in men with sarcopenia compared with those without sarcopenia." (PMID 36777353, 2023). "In our study, we noted lower values of inflammatory markers (CRP, CRP/albumin ratio, TNFα, IL-6, IL-1β, cfDNA) in the no-sarcopenia group, as opposed to the sarcopenia group." (PMID 37465171, 2023). "Compared to those without sarcopenia, participants with sarcopenia had lower BMI, albumin, and muscle thickness, as per ultrasonic imaging results but higher SARC-F questionnaire scores." (PMID 35237317, 2022).
sarcopenia (continued). "After PSM, the readmission group had higher NRS (P=0.001) and rate of sarcopenia (P=0.001), and lower albumin level (P=0.010) than the patients who were not readmitted." (PMID 35463676, 2022). "The present study combined the strengths and weaknesses of markers from previous studies, combining neutrophil, platelet and lymphocyte counts and albumin levels to form the SII-PNI score, and based on this score found that patients with higher scores were more likely to develop sarcopenia." (PMID 36046129, 2022). "The modeling revealed that the prevalence of sarcopenia was not influenced by age (p = 0.63), serum albumin (p = 0.64), or dialysis vintage (p = 0.59)." (PMID 36235729, 2022). "Regarding preoperative nutritional status, the mean value of serum albumin was 4.0 ± 0.4 g/dl (within normal limits), which was not significantly different between patients, with or without sarcopenia (3.9 ± 0.4 vs 4.1 ± 0.4 g/dl; P = 0.181)." (PMID 35445700, 2022). "Compared with those without sarcopenia, those with sarcopenia had lower TP (71.6 ± 5.3 vs. 72.3 ± 6.3), ALB (43.3 ± 3.3 vs. 44.5 ± 2.9), and PA (257.31 ± 126.01 vs. 278.38 ± 148.23), (P < 0.01)." (PMID 36419004, 2022). "Compared with those in the non-sarcopenia group, the patients in the sarcopenia group had lower body weight (kg) (P < 0.001), BMI (kg/m2) (P < 0.001), and preoperative blood albumin (P = 0.001)." (PMID 36684364, 2022). "Creatinine and BNP levels were significantly higher and albumin levels, eGFR, and hemoglobin levels were significantly lower in the sarcopenia group than in the non-sarcopenia group (P < 0.05)." (PMID 35313647, 2022). "These patients had a significantly lower body mass index (p < 0.0001) and serum albumin level (p = 0.0070) as well as a higher rate of advanced-stage cancer (p = 0.0062) than those without sarcopenia." (PMID 35611230, 2022). "The serum albumin, lean mass, fat free mass, and fat free mass indices were significantly lower in patients with sarcopenia than non-sarcopenic patients." (PMID 36307496, 2022). "Cox regression multivariate analysis demonstrated that sarcopenia, multiple tumors, maximal tumor diameter≥ 5cm, major venous thrombosis, sarcopenia, AFP ≥ 200 ng/ml, and albumin<3.5mg/dL were independent poor prognostic factors for overall survival in HCC patients receiving TACE." (PMID 36248997, 2022). "Of the systemic inflammation markers, sarcopenia and/or myosteatosis associated with elevated NLR (p = 0.005) and low albumin levels (≤35 g/L) (p = 0.018), but not with mGPS or serum cytokine levels." (PMID 35566781, 2022). "SI showed a significant linear correlation between SMI (r=0.495, p<0.001) and prealbumin (r=0.181, p=0.010) but not with albumin (r=0.130, p=0.063), indicating that SI was an ideal alternative biomarker to screen for sarcopenia." (PMID 35287579, 2022). "Subjects without sarcopenia at the time of follow‐up visit were more physically active and had higher levels of serum albumin and haemoglobin." (PMID 35698920, 2022). "In addition, indicators reflecting nutritional status, such as serum albumin (ALB), hemoglobin and sarcopenia have been identified as postoperative prognostic factors in patients with RCC." (PMID 35127784, 2021). "Higher blood albumin levels were found in the meta-analysis, which was statistically significant among the elderly adults who did not present sarcopenia compared to those who did." (PMID 34559500, 2021). "In addition, other variables, such as surgical type, hemoglobin, ALB, GLB, and AGR, were comparable between low and high AGS or sarcopenia and non-sarcopenia groups." (PMID 34631767, 2021). "Subjects with sarcopenia had higher baPWV, nutrition risk and lower ASMI, HS, GS, BMI, TG, serum ALB, and serum Cr than those without sarcopenia." (PMID 32228465, 2020). "We also did not evaluate surrogate parameters for sarcopenia, such as serum albumin or calf circumference, in relation to physical dysfunction, nor did we record the participants’ medications." (PMID 32102215, 2020).
sarcopenia (continued). "Selected parameters for muscle tissue computed tomography-scan derived and matched with BMI allowed to define the condition of sarcopenia; the mGPS was instead assessed through the level of C-reactive protein (CRP) and albumin (high mGPS was equal to CRP > 1.0 mg/dL and albumin < 3.5 g/dL)." (PMID 31766196, 2019). "Third, other parameters that were not assessed included the CRP-to-albumin ratio, estimated glomerular filtration rate, platelet-to-lymphocyte ratio, sarcopenia, and preoperative prealbumin concentration." (PMID 31429742, 2019). "There were also significant differences in previous chemotherapy, RT dose, serum albumin level, and total protein level between patients with and without pre-RT sarcopenia." (PMID 31681607, 2019). "In this context, it is interesting that several clinical studies have demonstrated a link between the specific pattern of increased CRP and decreased albumin concentrations with sarcopenia, frailty and vascular and non-vascular mortality in elderly subjects." (PMID 30733685, 2018). "Finally, age, ALB level, BR MT, Glh MT, and CMMC were independent predictors of sarcopenia." (PMID 39910436, 2025). "Second, we lacked comprehensive baseline data on renal function, albumin levels, and sarcopenia prevalence, which are factors that could affect both vitamin D metabolism and surgical recovery." (PMID 41148777, 2025). "Notably, people with sarcopenia have higher AST and ALT than those without sarcopenia, while their albumin and bilirubin levels are lower." (PMID 40686817, 2025). "Two hematological biomarkers, albumin (SMD = −0.58, 95% CI (−0.75, −0.42), K = 37, N = 18,178, I2 =94.2%) and hemoglobin (SMD = −0.59, 95% CI (−0.85, −0.33), K = 23, N = 6908, I2 =94.4%), were significantly negatively correlated with sarcopenia across all four classifications." (PMID 40507924, 2025). "We found that patient age, albumin level (ALB), brachioradialis muscle thickness (BRMT), gastrocnemius lateral head muscle thickness (Glh MT), and calf maximum muscle circumference (CMMC) were independent predictors of sarcopenia in hospitalized older patients." (PMID 39910436, 2025). "However, one study did show a significant positive and negative association with sarcopenia and INR and albumin respectively." (PMID 39172893, 2024). "Additionally, a meta-analysis of 33 160 community-dwelling residents indicated a negative correlation between serum ALB and Hb levels and the severity of sarcopenia and frailty." (PMID 40008206, 2024). "Interestingly, frail patients without sarcopenia had lower albumin values (3.080 ± 0.547) compared to those with sarcopenia and without frailty (3.294 ± 0.398)." (PMID 39795544, 2024). "Although the baseline levels of serum albumin, C-reactive protein (CRP), and interleukin 6 (IL-6) were comparable between patients with and without sarcopenia, the development of sarcopenia was significantly associated with lower albumin levels and higher CRP and IL-6 levels." (PMID 38797769, 2024). "Laboratory findings revealed significant differences between the groups, with lower albumin levels and muscle density and higher Chronic Liver Failure‐Sequential Organ Failure Assessment (CLIF‐SOFA) scores in the sarcopenia group than in the non‐sarcopenia group." (PMID 38965993, 2024). "Subjects with sarcopenia also have lower serum albumin values than non-sarcopenic subjects." (PMID 38674807, 2024). "In addition, we found a slight increase in serum globulin (GLB) and a slight decrease in serum Albumin (ALB) and albumin to globulin ratio (A/G) in patients with sarcopenia, although the absence of the significant difference between SAR and CON." (PMID 38188577, 2023). "Our present study is the first to have demonstrated a significantly higher CRP/albumin ratio in sarcopenia compared to no sarcopenia older adult, and the ratio could be used as one of the novel biomarkers of inflammation in sarcopenia." (PMID 37465171, 2023).